CSF1R (colony stimulating factor 1 receptor)
Diseases named in the same sentence as CSF1R in open-access papers (continued):
Sharing a sentence is not in itself a finding about the gene and the disease.
tumor (continued). "After CSF1R and CCR2 antagonism, they confirmed a significant reduction in tumor infiltrating monocytes and macrophages and found that tumor size decreased, an enhanced response to chemotherapy, and that hepatic and peritoneal metastasis decreased." (PMID 37575220, 2023). "Inhibitors of CSF1R can inhibit the infiltration of macrophages in the TME, reshape their polarity, promote CD8+ T-cell infiltration, and prevent tumor progression." (PMID 36884148, 2023). "Inhibiting CSF1R not only blocks TAM recruitment but also skews M2 to M1 phenotype, which effectively resulted in retarded tumor growth, inducing cytotoxic T-cell response and better prognosis with combinatorial chemotherapy." (PMID 38035101, 2023). "Therapies that block the CSF-1/CSF-1R axis and that, in general, chemokine-targeted therapies (antiCXCL12 or anti-CCL2) not only have the effect of acting directly on tumor growth and propagation but also target the TME formed by immune cells." (PMID 37958702, 2023). "In tumor tissues, the presence of M-CSF, also known as CSF1, promotes carcinoma growth and angiogenesis by a paracrine effect on the CSF1R." (PMID 37663266, 2023). "Combinational treatment of anti-PD-1 with PLX3397, an inhibitor of colony-stimulating factor-1 receptor (CSF-1R), increases the accumulation of CD8+ T cells in malignant cells and delays tumor progression." (PMID 38082437, 2023). "PLX-3397, a small molecule inhibitor of CSF1R, cKIT, and FLT3, has shown promise in reducing M2 macrophages and tumor burden when combined with adoptive cell transfer immunotherapy or other small molecule inhibitors." (PMID 37892995, 2023). "Yu’s group developed an intelligent nanodrug PFH@LSLP that can target CXCR4, which is highly expressed under tumor hypoxic conditions, and deliver both sorafenib and CSF1/CSF1R inhibitor PLX3397." (PMID 36903458, 2023). "A CSF-1R inhibitor, namely PLX-3397, was tested on tumor-bearing mice and examined for its efficacy in tumor control." (PMID 37886177, 2023). "Diminishing angiogenesis and tumor growth by depleting TAMs with approaches including CSF1 inactivation, CSF1 receptor (CSF1R) antibodies, and clodronate liposomes has been shown in a variety of tumor types." (PMID 37426676, 2023). "Multiple clinical trials are ongoing to evaluate the effects of CSF-1/CSF-1R blockade on TAM populations and tumor control in many both solid tumors and hematologic cancers." (PMID 37114134, 2023). "So far, one CSF1R inhibitor (pexidartinib) has obtained FDA approval but only in the setting of tenosynovial giant cell tumors, a tumor type that aberrantly expresses CSF1 in neoplastic cells due to chromosomal translocations involving the CSF1 gene." (PMID 37505292, 2023). "Recently, Salvagno and colleagues showed that CSF-1R blockade stimulates an intratumoral type I IFN response and enhances cisplatin anti-tumor effect in transgenic mouse model of BC." (PMID 36960065, 2023). "Preclinical studies have demonstrated that another CSF-1R inhibitor, BLZ945, inhibits tumor growth in different mouse models and its potential use in treating solid tumors is being studied in clinical trials." (PMID 36739406, 2023). "Genes associated with proliferation, and cell survival (BCL2L1), and tumor- cell growth (WT1) pathways for development of cancer were overexpressed, whereas molecules relevant to differentiation resistance (CSF1R) were underexpressed." (PMID 35246110, 2022). "For instance, in a mouse model of PDAC, the use of an anti-CSF1-R antibody in combination with antagonists of PD-1 and CTLA-4 enhanced antigen presentation and productive anti-tumor T cell responses leading to tumor regressions." (PMID 35163420, 2022).
tumor (continued). "For example, the inhibition of colony-stimulating factor 1 receptor (CSF1R) can selectively deplete TAMs from the TME, which results in increased tumor killing by resident T cells." (PMID 36291891, 2022). "A high expression of CSF-1/CSF-1R and a high density of TAMs and CD3+ T-lymphocytes create an immunosuppressive tumour milieu that is related to tumoral immune escape through the inhibition of T lymphocytes and to BC progression." (PMID 36294305, 2022). "Due to its high relevance for the tumor-permissive biology of TAM, the transmembrane tyrosine kinase colony-stimulating factor 1 receptor (CSF1R) is an attractive therapeutic target." (PMID 35565307, 2022). "b) CSF1R inhibition limited MPE in vivo by reducing vascular permeability and neoangiogenesis and impeding tumor progression." (PMID 35315360, 2022). "From results, these NPs were able to disassemble to small particles in response to low pH of tumor site 158 and facilitated the quick release of BLZ-945, which was then preferentially uptook by TAMs to contribute to TAMs elimination by CSF1R blocking." (PMID 36451865, 2022). "This study also found that PD-1/PD-L1 expression on TAMs and CTLA-4 expression on CD8+ T cells was increased in the presence of CSF-1/CSF-1R blockade, and the combination of PD-1 or CTLA-4 antagonists resulted in more significant tumor regression." (PMID 35874717, 2022). "The CSF-1R inhibitor and CXCR2 antagonist combination blocked tumor granulocyte infiltration and presented strong anti-tumor efficacy." (PMID 35585567, 2022). "Q702 treatment inhibited the phosphorylation of Axl and CSF1R in H1299 and M-NFS-60 tumor samples, respectively, indicating that Q702 inhibits Axl and CSF1R activation in a physiological setting." (PMID 36230744, 2022). "In a phase Ib study of PLX3397 which is efficacy for patients with advanced solid tumors, CSF-1R signaling is interrupted by PLX3397 and the M2-like TAMs is significantly reduced at tumor sites in patients." (PMID 35672862, 2022). "In the repopulation model, we aimed to assess the therapeutic effect of CSF-1R inhibition–induced depletion and subsequent repopulation on GAMM dynamics in an established tumor." (PMID 35115369, 2022). "Sustained CSF1R activation by its ligands in the TME results in polarization of the M2 TAM phenotype and promotes tumor progression, inhibiting immune-stimulatory signals; therefore, it has been considered as a promising therapeutic target." (PMID 36230744, 2022). "Surufatinib is a drug that targets tumor angiogenesis (VEGFR and FGFR1) and tumor immune evasion (CSF-1R)." (PMID 35874717, 2022). "Collectively, these results suggest that CSF1R+ macrophages promote MPE mainly by inducing vascular hyperpermeability, destabilizing tumor vessels, and favoring immune suppression." (PMID 35315360, 2022). "induced forced expression of the macrophage colony-stimulating factor 1 receptor (CSF-1R) to render CAR-T cells sensitive to CSF1, a monocyte recruiting chemokine enriched in various tumor tissues." (PMID 35211124, 2022). "Pexidartinib (PLX3397) is a multi-kinase inhibitor targeting CSF-1R that is FDA approved for the treatment of tenosynovial giant cell tumor, a rare CSF1-driven neoplasm." (PMID 36077755, 2022). "Pre- and on-treatment biopsies across multiple tumor types in patients being treated with cabiralizumab and nivolumab showed an increase of CD8 lymphocytes mirrored by a reduction of CD163+ CSF1R+ Mф (NCT02526017)." (PMID 36077813, 2022). "In vivo experiments using murine models demonstrate that stromal TAM depletion with CSF1R, a TAM differentiation/recruitment factor, can increase both the number of T-cells present in tumor islets and their motility." (PMID 35158750, 2022). "Other studies have demonstrated that CSF-1R blockades combined with CXCR2 antagonists, ICB or anti-VEGFR mAbs have better efficacy in tumor patients." (PMID 36246629, 2022).
tumor (continued). "By generating macrophage-specific CSF1R-KO mice, we showed that CSF1R+ macrophages promoted MPE by enhancing hyperpermeability of vessels and destabilizing tumor endothelium (by reducing VE-cadherin)." (PMID 35315360, 2022). "The first CSF1R blockade experiment in a mouse proneural GBM model showed a survival advantage in tumor-bearing mice and reduced tumor growth and invasion." (PMID 35920986, 2022). "The use of CSF1R inhibitors (GW2580) reduces myeloid cells in the TME of gliomas and significantly decreases the expression of chemokine CXCL7, thus inhibiting tumor growth." (PMID 35837284, 2022). "In a murine PDAC model, a small molecule inhibitor of CSF-1R (ACD7507) prevented tyrosine phosphorylation of CSF-1R, resulting in depletion of tumor macrophages, increased survival, and decreased tumor burden." (PMID 36077755, 2022). "We also showed that CSF1R inhibition limited MPE in vivo by reducing vascular permeability and neoangiogenesis and impeding tumor progression." (PMID 35315360, 2022). "A preclinical study of CSF-1R inhibition with BRAF inhibitors demonstrated that these therapies complement each other and produce a robust anti-tumour effect." (PMID 35359423, 2022). "The small molecule inhibitor of CSF-1R, PLX3397 (pexidartinib), led to the increased infiltration of lymphocytes into the tumor with higher IFN-γ secretion." (PMID 35345849, 2022). "After CSF-1R inhibition, TSPO signal was detectable mostly at the border of the tumor mass, in line with the imaging results, together with a few Iba1+ and TSPO+Iba1+ cells." (PMID 35115369, 2022). "Pexidartinib (CSF-1R inhibitor) was demonstrated to alter the distribution of TAMs in TIME and reduce tumor volume in a mouse model of lung adenocarcinoma." (PMID 35874717, 2022). "The genetic ablation of CSF1R+macrophages and the CSF1Ri treatment limited MPE, while tumor pleural dissemination was reduced only by the inhibitor." (PMID 35315360, 2022). "Inhibiting the accumulation of TAMs by antibody-mediated CSF1R blockade was paralleled by both increased infiltration of CD4+ and CD8+ T cells and tumor growth inhibition." (PMID 35158779, 2022). "Preclinical studies in murine cancer models have shown that CSF1R inhibitors can block the increased secretion of various cytokines in TME, leading to decreased MDSC accumulation, angiogenesis, and tumor burden." (PMID 35122833, 2022). "CSF1R+ macrophages promote MPE by enhancing pleural vascular permeability and destabilizing tumor endothelium." (PMID 35315360, 2022). "In experimental mouse models of lung adenocarcinoma, targeting CSF-1R with the drug PLX3397 (pexidartinib), which also inhibits two other tyrosine kinase receptors, KIT and FLT3, decreased tumor burden by modification of TAM distribution." (PMID 35053602, 2022). "Combinational therapies of CSF-1R and CXCR2 antagonist demonstrated stronger effects on tumor treatment." (PMID 34683963, 2021). "Antagonizing CSF-1R with a selective inhibitor (BLZ945) modulates the induction of human and murine suppressive MDSCs and efficiently limit tumor progression." (PMID 35003065, 2021). "For example, the blockade of CSF1/CSF1R pathway and CCL2/CCR2 axis prevented TAM recruitment and improved anti-tumor immunity." (PMID 34575463, 2021). "To confirm the finding of different IL2 expression in the groups of CSF1R c.1085 genotype A_A and A_G, we used anti-IL-2 specific antibody to stain IL-2 in CRC tumor samples." (PMID 34830445, 2021). "This indicates that using approaches targeting molecules of immunosuppressive myeloid cells such as CSF1R and TREM2 would partially affect the endogenous anti-tumor TAM component." (PMID 34220848, 2021).
tumor (continued). "Macrophage depletion, via colony-stimulating factor 1 receptor (CSF-1R) inhibition, has been shown to increase CD8+ T cell tumor infiltration in tumor-bearing mice, synergizing with anti-PD-1 treatment." (PMID 34188042, 2021). "Blocking CSF-1R with a CSF-1R tyrosine kinase inhibitor can reduce RCC proliferation and macrophage infiltration, which corresponds to a significant reduction in tumor volume." (PMID 34722262, 2021). "In vivo, the use of a CSF-1R tyrosine kinase inhibitor to block CSF-1R reduced RCC proliferation and macrophage infiltration, which was related to a significant reduction in tumor volume." (PMID 34722262, 2021). "Combination of CSFR1 inhibitor (PLX3397 or anti–CSF1R Ab) with anti-PD1 reduced TAM numbers, enhanced CD8 T cell infiltration, and consequently decreased tumor size." (PMID 34572013, 2021). "CX3CR1 and CSF1R are highly expressed in FCGR3A+ (CD16+) subset, which can be identified as an inflammatory phenotype in anti-tumor immune response." (PMID 33648605, 2021). "Inhibition of CCL2/CCR2 or CSF1/CSF1R signaling pathway can reduce the intratumoral infiltration of M2-TAM and inhibit tumor growth and metastasis." (PMID 34583750, 2021). "We selected four hub genes, LAPTM5, C1QC, CSF1R, and SLCO2B1, and analyzed their correlation with the tumor infiltration of 22 immune cell subsets using CIBERSORT and the prognosis of different immunity-related LUSC patient subtypes." (PMID 33428598, 2021). "At 72 h after [89Zr]Zr-DFO-N-suc-IgG2a administration, there was a higher presence in tumor and blood pool and less in the liver and spleen than for [89Zr]Zr-DFO-N-suc-CSF1R-mAb." (PMID 34976826, 2021). "Once recruited to the tumour site and activated via CSF-1R, pro-tumourigenic GAMs secrete epidermal growth factor (EGF) to stimulate tumour cell invasion." (PMID 33803414, 2021). "We observed that the blockade of CSF-1R resulted in the marked enhancement of combined IT, but only in TC-1/A9 tumors, which could be connected with the involvement of TAMs in the IT of this tumor type; in TC-1/dB2m tumors, the anti-tumor effect of TAMs was not proved." (PMID 34205330, 2021). "The CSF1/CSF1R axis is positively correlated with VEGF-A expression, which contributes to tumor angiogenesis." (PMID 33406733, 2021). "It was identified in culture that tumour-derived factors such as IFN-γ and GM-CSF can protect GAMs from CSF-1R blockade." (PMID 33803414, 2021). "Other studies demonstrated that the co-inhibition of CSF1-R and SHP2 using nanoparticles loaded with inhibitors for tumor TAM activation and enhancement of phagocytosis is an effective strategy for macrophage-based antitumor immunotherapy." (PMID 33777940, 2021). "Analysis of normal and tumor tissue from 6 np, 9 pregnant, 11 lactating, 8 involuting, and 10 regressed women aged ≤45 years.IHC, IF, imaging of CD68, CSF-1R, and F4/80." (PMID 33649008, 2021). "As an example, 57.1% and 60% of the samples show the same expression levels for CSF1R and PD1 in primary and recurrent tumor situations." (PMID 34063518, 2021). "Our results show that cases with high CSF-1R expression on cancer cells, but not macrophages, are associated with inferior survival, particularly in the common hormone receptor-positive breast cancer group, which persists even in the presence of an active anti-tumor host immune response." (PMID 34830923, 2021). "In tumor environment of activated ccRCC, the proportion of CD86+CSF1R+ monocytes were significantly increased." (PMID 34239350, 2021). "In this work, we propose a combination therapy strategy by co-applying a CSF1R inhibitor (BLZ945) and MHT to remodel the tumor immune microenvironment, yield the synergistic MHT-immunotherapy, and thus inhibit tumor growth and recurrence." (PMID 34093858, 2021). "The small molecule BLZ-945 specifically inhibits CSF-1R phosphorylation and blocks CSF-1-mediated signal transduction in TAMs, leading to apoptosis and improving CTC infiltration in the tumor 96,97." (PMID 34158855, 2021).
tumor (continued). "For example, using mouse glioblastoma as an experimental object, researchers used CSF-1R inhibitors to reduce the expression of Arg1 (arginase 1) and Mrc1 (CD206, mannose receptor) genes in the TME, thereby inhibiting tumor growth and metastasis." (PMID 34683963, 2021). "Inhibition of CSF1R has been proposed to be an effective target for blocking monocytes and TAM that infiltrate the tumor stroma and support tumor growth." (PMID 33842370, 2021). "Some M1 markers (IL1A, IL1B, CD86), M2 markers (CCL18, MRC1/CD206, CSF1R), and TAM markers (HLA-DR, IL1RN, CD163, ITGAM, SIGLEC1/CD169) were highly expressed on both tumor and non-tumor macrophages." (PMID 33918618, 2021). "When macrophages were depleted with anti-CSF-1R therapy, CD8 T cells successfully infiltrated the tumor to interact with malignant cells and delay tumor progression." (PMID 33968034, 2021). "In our model CSF-1R inhibition also cooperates with standard antibody therapy anti-CD20, hampering tumor growth." (PMID 33731849, 2021). "But anti-CSF1R treatment for AML should consider the major CSF1R-expressing population in BM microenvironment, and avoid to eliminate anti-tumor population and impair T cell response." (PMID 33648605, 2021). "Recently, it has been demonstrated that, by inhibiting CSF-1R, TAMs can reprogram from the M2 to the M1 phenotype in the TME, work in concert with T cells, and participate in tumor elimination." (PMID 34205330, 2021). "Similar anti-tumor activity was observed in a colorectal cancer model (MC38) treated with anti-CD40 and CSF-1R inhibition." (PMID 33804039, 2021). "In animal models, combination of CSF1R blockade and classical immunotherapy agents (as anti-PD1 and anti-CTLA4) has shown a reduced tumour growth compared to single treatment." (PMID 33627655, 2021). "We found that tumor-infiltrating CD33high cells showed high gene expression levels of CD36, CD14, FUT4 (CD15), CD80, CD86, CSF1R and immune checkpoint ligand genes including CD274 (PD-L1), LGALS9 (galectin-9), PVR and VSIR." (PMID 33000418, 2021). "Researchers used CSF-1 receptor (CSF-1R) inhibitors to target TAMs in a mouse GBM model, which significantly improved mouse survival and tumor regression." (PMID 35071016, 2021). "TREM2 is expressed on CSF1R+ TAMs and is modulated by CSF1 and its blockade on TAMs results in delayed tumor growth, remodeling of the tumor immune contexture and increased ICI efficacy." (PMID 34220848, 2021). "We demonstrated the high specificity of our NBCSF–1R on targeting CSF-1R overexpressing macrophages and HCC tumor margin." (PMID 32760707, 2020). "TAMs interact with CD8+ T cells to trap them in the tumor stroma and TAM depletion using a CSF-1R inhibitor increased CD8+ T cell migration and infiltration into tumors." (PMID 32326073, 2020). "In turn, simultaneous treatment with both a CSF1R inhibitor and a CXCR2 inhibitor targeting PMN-MDSCs effectively decreases tumor growth." (PMID 32801364, 2020). "The combination of CSF1R and IDO inhibitors (PLX647 and indoximod, respectively) has been proposed as another approach that was found to elicit tumor regression by stimulating T-cell recruitment." (PMID 33212945, 2020). "FGFR2, VEGFR2, CSF1R, and EGFR are tyrosine kinases that are constitutively activated in cancer cells to promote tumor progression and angiogenesis." (PMID 33488754, 2020). "Combined treatment with the FATP2 inhibitor lipofermata and checkpoint inhibitors anti-CTLA-4 or anti-CSF-1R inhibitors abolished the inhibitory activity of PMN-MDSCs and blocked tumor progression in mice." (PMID 32942545, 2020). "This inhibitor has specificity against CSF1R but also the related receptor FLT3 and has been shown to reduce macrophage numbers and limit tumour growth in several models of transplanted tumours as well as in a FLT3-dependent subset of AML." (PMID 32581720, 2020).